CCND1 (cyclin D1)
Diseases named in the same sentence as CCND1 in open-access papers (continued):
Sharing a sentence is not in itself a finding about the gene and the disease.
tumor (continued). "Our data demonstrated that a high level of cyclin D1 expression, together with poor tumor cell differentiation and advanced AJCC stage, predicted high risk of postoperative distant metastases in operable ESCC." (PMID 27145270, 2016). "Although an effect of RT, in terms of tumor weight and tumor volume, was observed in 22Rv1 expressing cyclin D1, a negligible improvement in the TTP was documented in this xenograft model [13.0." (PMID 26689991, 2016). "While the UPR is considered important for tumor progression, there is potential for tumor suppressive activity given it antagonizes cyclin D1." (PMID 27977682, 2016). "Many genetic abnormalities have been revealed in tumor cells and altered expression of cell cycle regulators like cyclin D1 and cyclin-dependent kinase (CDKs)." (PMID 26786409, 2016). "miR-33a is regarded as a tumor suppressor that targets cancer-associated genes involved in cell proliferation and cell cycle progression, such as CDK6, CCND1 and Pim-1." (PMID 27285759, 2016). "Western blot analysis showed that the BHX treatment markedly reduced the expression of cyclin D1 and c-myc in the tumor cells." (PMID 27910912, 2016). "These tumours are characterized by co-amplification of CCND1 and PAK1 at 11q13–14, and have previously been shown to be resistant to neo-adjuvant cytotoxic chemotherapy." (PMID 27161491, 2016). "There is evidence that nuclear accumulation of β-catenin results in accelerated tumor cell proliferation and tumor progression through the transcriptional activation of target genes including c-Myc, cyclin D1 and COX-2." (PMID 27506388, 2016). "Given that cyclin D1 overexpression has been shown to correlate with early cancer onset and tumor progression, FGS can be used broadly to enhance the efficacy of a chemotherapeutic drug such as CDDP in treating various cancer." (PMID 27721894, 2016). "We found that long-termed treatment of berberine increases its potency in suppressing tumor cell growth as well as in potentiating Cyclin D1 turnover." (PMID 27854312, 2016). "EWSAT1's function as an oncogene to facilitate tumor progression was partially attributed to its ability to acting as a ceRNA for miR-326/330-5p clusters, and subsequent to activating of the cyclin D1 signaling pathway in NPC." (PMID 27816050, 2016). "We observed that Ccnd1 was expressed in 13.9% of Brg1-negative tumor cells and was expressed in 72.7% of Brg1-positive tumor cells; this difference was statistically significant (p=4.0E-7)." (PMID 28105458, 2016). "All these results suggest that the sequestration of an active complex Ccnd1-Cdk4 in the membrane increases the invasiveness of tumor cells." (PMID 27105504, 2016). "Cyclin D1 overexpression has been correlated with early cancer onset and tumor progression in many cancers." (PMID 27095572, 2016). "Eleven out of 13 papillary microcarcinomas showed nuclear staining of cyclin D1 with grade 3 diffuse nuclear staining seen in 5 (38%) of the tumours." (PMID 25907675, 2015). "Cyclin D1 was found to be expressed predominantly in the nuclei of tumor cells in DMBA control animals." (PMID 26703530, 2015). "These tumors had a borderline finding in the metastases with 2 centromeres and 4 CCND1 signals per tumor cell." (PMID 25649416, 2015). "These CTLs efficiently recognized target cells pulsed with their cognate peptide and cyclin D1 expressing tumor cell lines in an HLA-A*0201-restricted manner." (PMID 25888530, 2015).
tumor (continued). "The experiments using clinical HNSCC samples demonstrated that GALR1 methylation was significantly correlated with reduced survival rates, tumor stage, lymph node status, increased tumor size, cyclin D1 expression and p16 methylation." (PMID 26251921, 2015). "The inhibition of protein expressions related to the cell proliferation (cyclin D1) and tumor invasion (MMP-9 and RANKL) was more severe in the pretreatment group compared with that of the concurrent treatment group." (PMID 26487364, 2015). "Cyclin D1 has been reported to play a direct role in the regulation of apoptosis and, thus, in the resistance/sensitization of tumor B cells to anticancer drugs." (PMID 25881299, 2015). "In accordance with these findings, Sirtinol abrogated the increase of both Cyclin D1 and the proliferative index Ki-67 upon G-1 treatment, as assessed in tumor homogenates." (PMID 26225773, 2015). "GISTIC analysis defined significant common regions of amplification and deletion that harbour multiple oncogenes (for example, MYC and CCND1) and tumour suppressors (for example, SMAD4 and CDKN2A)." (PMID 25855536, 2015). "We selected MYC and CCND1 mRNA levels as these two genes are considered extremely relevant in the G0 – G1 cell cycle transition and S phase entry, being key factors for tumor development, growth and progression." (PMID 25671297, 2015). "Recent studies suggest Cyclin D1 also plays a key role in promoting cellular migra­tion of epithelial cells, which shows the new roles of Cyclin D1 in tumor progression and metastasis." (PMID 25823925, 2015). "More importantly, HLA-A*0201 matched, primary cyclin D1 positive tumor cells were efficiently recognized by cyclin D1-specific CTLs." (PMID 25888530, 2015). "Immunohistochemical staining of the cell cycle regulatory protein cyclin D1 was found to be higher in tumor section from metformin administered mice." (PMID 26484566, 2015). "(ii) In contrast, significantly down-regulated genes from another group were associated with tumor metastasis suppression (KISS1), retinoblastoma (Rb) gene positive regulator (CCND1), and a canonical Wnt antagonist (LRP6 through DDK1)." (PMID 26079538, 2015). "As expected, we found that HER2 downstream mediators, including PLCγ, STAT5, AKT and Cyclin D1, were decreased in tumor tissues lysates." (PMID 26375550, 2015). "EVO markedly reduced cyclin D1 expression (p < 0.001) and increased the number of apoptotic tumor cells (p < 0.001) compared with untreated controls." (PMID 26207989, 2015). "Consistent with previous data, the induction of cyclin D1a in Ccnd1+/+ lines was weakly tumorigenic, increasing tumor formation of that cell type by ~20% (Fig3F)." (PMID 25787974, 2015). "The cyclin D1-Trop2 mRNA is a potent oncogene as it transforms primary cells in vitro and induces aggressive tumor growth in vivo in cooperation with activated RAS." (PMID 26000093, 2015). "In vivo, we consistently observed that NDRG1 suppression in HCC xenografts decreased β-catenin levels and its downstream target Cyclin D1, with concomitant tumor growth inhibition." (PMID 26359353, 2015). "Treatment of mice with honokiol resulted in a marked decrease in the expressions of cyclin D1 and cyclin D2 and reduced expressions of Cdk4 and Cdk6 in tumor samples obtained from honokiol-treated mice compared to tumor samples from control mice." (PMID 26020804, 2015). "FOXO1 up-regulates p27 and p21 to down-regulate the cell cycle regulator cyclin D1, which results in the cell cycle arrest, and plays a potential role in tumor suppression." (PMID 26289446, 2015). "Previous in vitro studies have shown similar results with a statin induced up-regulation of p27 and reduced levels of cyclin D1 in various tumor cell lines." (PMID 25925673, 2015).
tumor (continued). "YAP1 overexpression in the intestine correlates with downregulation of the tumor suppressor PTEN, exerting its tumor-suppressive functions in part by decreasing Cyclin D1 levels." (PMID 25601544, 2015). "Cyclin D1 is frequently deregulated in various cancers, including malignant hemopathies, and tumor cells display uncontrolled cell proliferation." (PMID 25881299, 2015). "Similar changes in cell cycle regulators cyclin D1 and p21 as well as EMT-associated genes including E-cadherin, N-cadherin, and vimentin were observed in tumor tissues by IHC." (PMID 25887760, 2015). "Because CTLs are a major effector arm of anti-tumor immunity, we analyzed in greater detail on the induction of cyclin D1-specific CD8+ T cells from PBMCs of healthy donors." (PMID 25888530, 2015). "The expression of CCND1 in the pre-treatment samples was significantly correlated to response in tumor cell proliferation (P = 0.02; Mann–Whitney)." (PMID 25925673, 2015). "Western blot assay confirmed that PTEN expression was also decreased in tumor tissues, whereas p-Akt, c-Myc and CCND1 were increased after the treatment of nano-anti." (PMID 25691053, 2015). "Cyclin D1 expression in terms of nuclear intensity was significantly decreased (P = 0.008) after statin treatment in paired tumor samples." (PMID 25925673, 2015). "The anti-tumour action of LDFI was associated with the inhibition of several leptin-induced pathways such as JAK2, STAT3, AKT and MAPK and a reduction in Cyclin D1 expression." (PMID 25721149, 2015). "On the other hand, tumor sections from rats that had PE at 1.0 and 5.0 g/kg exhibited moderate and substantial reduction in the expression of cyclin D1, respectively." (PMID 26703530, 2015). "Our study demonstrated that expression of the PPIase CYPJ is likely to facilitate tumor growth by promoting cell cycle transition from G1 to S phase in a PPIase-dependent manner through the upregulation of cyclin D1." (PMID 26020957, 2015). "We also studied the roles of CYPJ in cell cycle, cyclin D1 regulation, in vitro and in vivo tumor growth." (PMID 26020957, 2015). "Western blots assaying xenografted tumor lysates showed that AKT-S6 activations as well as cyclin D1 expression were significantly inhibited by VS-5584 or plus ABT-737 treatment in vivo, which are consistent with the in vitro findings." (PMID 26204252, 2015). "RT-PCR analysis was performed to determine the expression of cyclin D1 mRNA in various tumor, PML and normal samples." (PMID 25645517, 2015). "miR-16 has multiple cell proliferation targets, such as Cyclin D1 and Cyclin E1; supporting the premise that it is a tumor suppressor miRNA." (PMID 26440311, 2015). "The present study aimed to evaluate the role of a cell cycle regulator like cyclin D1 in these tumours along with assessment of other well established PTC markers like galectin-3, HBME-1, CK19." (PMID 25907675, 2015). "As expected, there was a down regulation of cellular proliferation molecules CDK1, CDK2, CDK4, CDK6, Cyclin D1, Cyclin E and Cyclin B1 and upregulation of p16 and p21 in the xenograft tumor tissues by IHC." (PMID 26590805, 2015). "Immunohistochemical evaluation of cyclin D1 was achievable in 30 of the 42 paired samples restricted by insufficient amount of tumor tissue in the remaining core biopsies." (PMID 25925673, 2015). "In this analysis, we used galectin-3, HBME-1, CK19, Ki67 and cyclin D1 to evaluate the borderline nature of this tumour." (PMID 25907675, 2015). "Cyclin D1 is a another key regulator for the G1 to S transition and tumor progression that activates cyclin D-CDK4 complex to enhance the transcription of cell cycle related genes." (PMID 25764126, 2015).
tumor (continued). "As a reduction in Bmal1 increases proliferation and cyclin D1 expression in both murine cells and tumours, as well as decreasing apoptosis." (PMID 25822259, 2015). "Corresponding frozen tumor sample pairs were analyzed for expression of the genes coding for cyclin D1 and p27, CCND1 and CDKN1B, respectively." (PMID 25925673, 2015). "Our earlier study reveals a unique role of SHP in inhibiting cell growth through repressing Cyclin D1 expression, thereby providing a molecular basis for tumor suppressor function of SHP during HCC development." (PMID 26504773, 2015). "The gene expression of CCND1 was found to be significantly correlated to response in tumor cell proliferation, indicating a difference in the response to statins between cancers with or without CCND1 overexpression." (PMID 25925673, 2015). "We found that both healthy individuals and MCL patients have a broad repertoire of cyclin D1-specific T cells thus supporting the utility of cyclin D1 as a tumor antigen for immunotherapy." (PMID 25888530, 2015). "Over-expression of miR-195 down-regulate the expression of Cyclin D1 protein, suggesting that miR-195 functions as tumor suppressors probably through down-regulating CCND1 in OS." (PMID 25823925, 2015). "Paradoxically, MM patients with cyclin D1-expressing tumor cells have a good prognosis and a longer overall survival." (PMID 25881299, 2015). "Further, CCND1 can enhance tumor progression, at least in part, by an increased level of transcription of FGFR1 and FGFR2 via E2F." (PMID 25596748, 2015). "Forty-two patients completed all study parts, and immunohistochemical evaluation of ER and PR was achievable in 30 tumor pairs, HER2 in 29 tumor pairs, cyclin D1 in 30 tumor pairs and p27 in 33 tumor pairs." (PMID 25925673, 2015). "Etodolac negatively regulates PPARγ function which then downregulates cyclin D1 leading to tumor growth inhibition." (PMID 26275572, 2015). "As the xenografts increased in size over time and had vascularized after four days following transplantation, we evaluated the effect of NO on Vascular Endothelial Growth factor-A (Vegfa) and Cyclin D1 gene expression and on tumor growth." (PMID 25768009, 2015). "DCs loaded with whole tumor cells or with selected peptides can elicit cyclin D1-specific CD8+ T cells that kill MCL tumor cells." (PMID 25888530, 2015). "Mechanistic investigations reveal that a miR-197-mediated CKS1B/STAT3 axis exerts tumor progression regulated by various oncogenic genes (Bcl-2, c-Myc, and cyclin D1), and PD-L1 is a putative biomarker of this axis." (PMID 25597412, 2015). "In multivariate analysis, taking into account age, tumor site, smoking, tumor stage, and cyclin D1 expression, only GALR1 methylation and stage were significant predictors of poor survival." (PMID 26251921, 2015). "The percentage of cyclin (CCN) alteration varies by tumor type; for instance, in previous studies, CCND1 amplification ranged from 15–40%." (PMID 25596748, 2015). "Doses of bardoxolone methyl that increased expression of the classic Nrf2 target gene NQO1 and decreased tumor levels of NF-κB and cyclin D1 were well-tolerated by patients with advanced malignancies in a phase 1 trial (ClinicalTrials.gov ID: NCT00529438)." (PMID 25897966, 2015). "Both groups, DM-1 monotherapy and DTIC+DM-1, revealed a tumor burden reduction of about 60%, partly via cell cycle arrest due to cyclin D1 and Ki67 decrease." (PMID 25742310, 2015).
tumor (continued). "γ-Tocotrienol can inhibit the angiogenesis of SGC-7901-CM-induced HUVECs, which is of fundamental importance in tumor growth, and the inhibitory effect is related to decrease the β-catenin and cyclin D1 activity." (PMID 25807493, 2015). "Cyclin D1 was found to be 1.3 to 2.7 fold overexpressed in 6 out of 7 tumor cell lines with respect to Nthy-ori 3–1, with the exception of KAT-18, in which it was found less expressed." (PMID 26431489, 2015). "The Cyclin D1 expression level was low in the tumor samples of FBXO31 overexpression group, which was similar with what we observed in vitro." (PMID 25115392, 2014). "The aim of the present study was to use immunohistochemistry to determine the expression patterns of PTEN, p27 and Cyclin D1 in normal and tumor epithelium in stage II/III CRC patients." (PMID 25202365, 2014). "Sp1 regulates several cellular functions and influences tumor growth by controlling expression of genes related to tumor growth and development such as cyclin D1, c-Jun, and c-Myc34." (PMID 25418289, 2014). "DACH1 protein abundance was inversely correlated with the expression of PCNA and cyclin D1, tumor grade, and TNM stage." (PMID 25322986, 2014). "miRVec-125b -transfected cells were tumourigenic in vivo, but the tumours showed an increased rate of senescence and decreased amount of proliferating cells, as measured by Ki67 and cyclin D1 staining." (PMID 24762088, 2014). "In cervical squamous carcinoma, most invasive tumour cells expressed cyclin D1 and showed a reduction in E-cadherin and beta-catenin staining." (PMID 25477004, 2014). "Tamoxifen treatment significantly altered the hormone receptor expression levels of the tumor, while additionally upregulating Bcl-2 and Cyclin D1." (PMID 23755153, 2014). "From the literature, C/EBPβ appears to be involved in tumor cell proliferation through regulation of cyclin D1 and its target genes." (PMID 25402211, 2014). "In contrast, the ERβ forms heterodimers with the ERα blocking their proliferative activity by suppression of oncogenic transcription factors (e.g. c-myc, cyclin D1 e cyclin A) and by stimulating the expression of tumour suppressing genes (e.g. p21 e p27)." (PMID 24720724, 2014). "Second, although immunohistochemistry was the most commonly used method for detecting cyclin D1 in situ, RT-qPCR method has also been used for the evaluation of the levels of cyclin D1 gene or mRNA expression in tumor tissue." (PMID 24728073, 2014). "Taken together, we found that overexpression of SOX7 suppressed tumor formation by proliferation inhibition via down-regulation of cyclin D1 and c-myc." (PMID 24816720, 2014). "CCND1 is astrong candidate for driving ERα + tumor formation in both our models, since it iscommonly amplified in ERα + tumors and activates ERα in the absence of hormone." (PMID 25527189, 2014). "Co-expression of cyclin D1 and Ki-67 was observed in the basal to suprabasal cells, and numerous cyclin D1-positive and Ki-67-negative cells existed toward the central section of the tumour." (PMID 24944679, 2014). "In cancer, several oncogenes and tumour promoters are translationally controlled by hnRNPA1, including cMYC, Cyclin D1, FGF-2, XIAP and BCL-XL (this report), all of which possess IRESs in their mRNAs." (PMID 25324306, 2014). "The expression of cyclin D1 (Santa Cruz Biotechnology, Santa Cruz, CA) is found in the developing tumor and the mammary gland of Kunming mice." (PMID 25230850, 2014). "Tumor cells are highly proliferative; therefore we explored the expression of cyclin D1 as a biomarker for cell proliferation." (PMID 23755153, 2014). "Dysregulation of cyclin D1 immediately contributes to tumor progression in some animal models, further demonstrating a connection between cyclin D1 and carcinogenesis." (PMID 24618206, 2014).